METTL3 (methyltransferase 3, N6-adenosine-methyltransferase complex catalytic subunit)
Diseases named in the same sentence as METTL3 in open-access papers (continued):
Sharing a sentence is not in itself a finding about the gene and the disease.
lung cancer (continued). "Moreover, in lung cancer, another aggressive neoplasm, METTL3 was shown to act as an oncogene, inducing tumor growth and proliferation, also promoting translation of important genes such as epidermal growth factor receptor (EGFR) and tafazzin (TAZ)." (PMID 30428628, 2018). "It is also possible that METTL3 could be acting in an m6A-independent manner as has been shown in lung cancer cells." (PMID 30131850, 2018). "However, the exact roles of METTL3 and m6A methylation in carcinogenesis induced by chronic chromium exposure and lung cancer development remain unclear." (PMID 41362669, 2026). "One study reported that metformin decreased the activity of DNMTs on the methyltransferase-like 3 (METTL3) promoter (an enzyme that causes m6A modifications in RNA), decreasing its methylation and favoring its expression and activity to promote let-7b expression in lung cancer cells." (PMID 38004379, 2023). "Moreover, METTL3-mediated autophagy-induced resistance to gefitinib could be reversed by β-elemene in lung cancer." (PMID 35794625, 2022). "This suggests that METTL3 may be a new target for lung cancer therapy." (PMID 35518355, 2022). "Therefore, we summarize the recent findings of METTL3 in the tumorigenesis of lung cancer." (PMID 35331234, 2022). "Similarly, METTL3 has been shown to mediate apoptosis by regulating Bcl-2 in lung cancer." (PMID 35141221, 2022). "In addition, METTL3 can also act as a tumor suppressor in lung cancer." (PMID 35331234, 2022). "In addition, the expression of METTL3 is up-regulated in lung cancer, wherein simvastatin treatment can attenuate this increased expression, which can in turn inhibit the malignant progression of lung cancer." (PMID 33428597, 2021). "Thus, METTL3 plays an important role in the occurrence and development of lung cancer." (PMID 33643384, 2021). "In addition, previous study indicated that METTL3 could facilitate the cleaving of miR-143 precursor to form mature miRNA in lung cancer." (PMID 34774019, 2021). "Notably, these studies demonstrate that METTL3 may act in a tumorigenesis role in lung cancer via not only target mRNA and miRNA but also by being modified by other genes." (PMID 34381710, 2021). "However, in another study on lung adenocarcinoma, METTL3 expression was elevated and could promote growth, survival, and invasion of human lung cancer cells." (PMID 31429529, 2019). "Further, METTL3 expression and m6A RNA methylation levels are enhanced during TGFβ-induced EMT in lung cancer." (PMID 40338154, 2025). "Scratch wound healing assays demonstrated that METTL3 enhances the migration of NSCLC cells, supporting its potential role in promoting lung cancer metastasis." (PMID 38238831, 2024). "In various tumor types, METTL3 typically functions as an oncogenic factor, including acute myeloid leukemia (AML), lung cancer, HCC, among others, while exhibiting an anti-oncogenic role in endometrial cancer." (PMID 39098905, 2024). "In lung cancer, for NSCLC, METTL3 promotes autophagy by upregulating the expression of LC3B, ATG5, and ATG7, protecting drug-resistant cells from death and leading to the development of resistance to gefitinib." (PMID 39468015, 2024). "Further studies indicated that METTL3 m6A methyltransferase regulates JunB mRNA and c-Jun protein expression at 3’-UTR in TGF-β1 induced EMT in lung cancer, respectively." (PMID 37731821, 2023). "Correlation analysis indicated that the expression level of GLI1 is positively correlated to that of IGF2BP2, METTL3/14, and SOX2OT in lung cancer bulk tumor." (PMID 37149646, 2023). "For example, in lung cancer, the stability of MALAT1 was increased by its hyper m6A modification level induced by METTL3." (PMID 37029420, 2023). "According to the current study, LINC00969 promotes gefitinib resistance in lung cancer by simultaneously binding to EZH2 and METTL3." (PMID 37156816, 2023). "The expression of the METTL3 gene is reduced, whereas that of the IGF2BP2 gene is increased in lung cancer." (PMID 37915034, 2023).
lung cancer (continued). "Previously, we have shown that JUNB is one of the important TFs regulated by METTL3 m6A methyltransferase during TGF-β-induced EMT of A549 and LC2/ad lung cancer cell lines." (PMID 36183833, 2022). "METTL3, RBM15, KIAA1429, YTHDF1, YTHDF2, HNRNPA2B1, HNRNPC, and IGF2BP1/2/3 expression levels in lung cancer tissues are significantly higher than those in normal tissues." (PMID 35518355, 2022). "Thus, METTL3 could act as a potential therapeutic target for lung cancer." (PMID 35331234, 2022). "METTL3 promotes the maturation of miR-143-3p to target the vasopressor (VASH) 1 promoter and inhibit its expression in lung cancer." (PMID 35572524, 2022). "In lung cancer epithelial-mesenchymal transition (EMT) models mediated by TGF-β, METTL3 markedly accelerates the EMT process." (PMID 35331234, 2022). "The results showed that the m6A level, as well as the methylase METTL3 were both significantly elevated in LUAD patients and lung cancer cells." (PMID 34996469, 2022). "After elucidating the critical roles of Mettl3 and ALKBH5 in mice and murine lung cancer cells, we next evaluated their functions in human LUAD cells." (PMID 35078505, 2022). "METTL3 overexpression can activate the PI3K/AKT/mTOR signalling pathway and mTOR-mediated protein synthesis in cancer cells to promote lung cancer progression." (PMID 36276113, 2022). "We have so far demonstrated that the m6A regulation of JUN and JUNB by METTL3 plays a critical role in the expression levels of them, thereby affecting the EMT-inducing gene expression program of A549 and LC2/ad lung cancer cells." (PMID 36183833, 2022). "Methyltransferase Like 3 (METTL3), acting as an oncogene in lung cancer, upregulated EGFR and TAZ expression and promoted growth, survival, and invasion of human lung cancer cells." (PMID 34827123, 2021). "provided evidence that METTL3-mediated miR-143-3p upregulation enhanced VASH1 repression, which thereafter triggered brain metastasis and the angiogenesis of lung cancer." (PMID 34722298, 2021). "To explore the role of METTL3 in primary gefitinib resistance, we examined the PI3K/AKT pathway which is related with lung cancer growth and resistance." (PMID 33491264, 2021). "In the cytoplasm of lung cancer cells, METTL3 enhances translation efficiency of mRNA by recognizing the m6A in 3′UTR based on the interaction between METTL3 and eIF3h which are co-overexpressed in many types of cancer." (PMID 34103054, 2021). "METTL3 can promote the expression of multiple oncogenes such as BRD4, EGFR, TAZ, MAPKAPK2, and DNMT3A in human lung cancer cells." (PMID 34206803, 2021). "The increased levels of RNA m6A modification and METTL3 expression were observed during the TGF-β-induced EMT in A549 and LC-2/ad lung cancer cells." (PMID 34638933, 2021). "Overall, these studies highlight the critical role of METTL3 expression in regulating the EMT-related oncogenes, the tumorigenicity of lung cancer cells, and in promoting lung cancer metastasis." (PMID 34638933, 2021). "We found that METTL3 influences the expression of MET by integrating with MET to regulate PI3K/AKT pathway, which affect the response of lung cancer cells to gefitinib." (PMID 33491264, 2021). "We also tested the expression of m6A writers METTL3, METTL14, and WTAP and of erasers ALKBH5 and FTO after the treatment of IL-37 in A549 cells and lung cancer tissues." (PMID 33489865, 2020). "Dysregulation of m6A “writer” protein, methyltransferase-like 3 (METTL3) and methyltransferase-like 14 (METTL14), has been reported in liver cancer, lung cancer and glioblastoma." (PMID 32111213, 2020). "Beside Wnt signaling, previous studies demonstrated that METTL3 and m6A levels contribute to EMT in lung cancer." (PMID 32719721, 2020). "We also showed the expression of m6A writers METTL3, METTL14, and WTAP and erasers ALKBH5 and FTO in A549 cells and lung cancer tissues after the treatment of IL-37." (PMID 33489865, 2020).
lung cancer (continued). "METTL3 silencing expedites cell apoptosis via AKT signalling pathway and inhibits the proliferation, migration and invasion of lung cancer cells." (PMID 33029866, 2020). "We first evaluated METTL3 expression in lung cancer tissues and non-cancerous lung tissues (control subjects) using The Cancer Genome Atlas (TCGA) database." (PMID 39309428, 2024). "One example is miR‐338‐5p, which acts as a negative modulator of METTL3, suppressing the methylation modification of oncogenes and consequently impeding the proliferation of lung cancer cells." (PMID 38706740, 2024). "m6A regulators, including METTL3, FTO, and IGF2BP2, act as tumor promoters through the C-myc pathway in an m6A-dependent manner to promote the growth, invasion, migration, and progression of various tumors, such as BC, lung cancer, and GC." (PMID 39199429, 2024). "Overexpression of METTL3 in lung cancer cells activates the PI3K/AKT/mTOR pathway and mTOR-mediated protein synthesis, promotes the proliferation and metastasis of cancer cells, and is a poor prognostic factor for lung cancer patients." (PMID 39289775, 2024). "Additionally, stimulation of HBE cells with CSE has been shown to elevate METTL3 levels and enhance E‐cadherin expression and epithelial–mesenchymal transition (EMT), potentially fostering lung cancer development." (PMID 39580709, 2024). "Some research found that ALKBH5 knockout resulted in spermatogenesis defects due to elevated spermatocyte apoptosis; disruption of the transcription process by METTL3 and METTL14 could lead to lung fibrosis and lung cancer metastasis." (PMID 38133427, 2023). "Functional analysis corroborated that GLI1 acted as a downstream target of METTL3/14/IGF2BP2, and GLI1 silencing could block the oncogenicity of lung cancer stem-like cells." (PMID 37149646, 2023). "In this finding, we further elucidated that m6A YTHDF1 mediates the translation of FTH increased and altered by disorder of METTL3 and, thereby, accelerates tumorigenesis in lung cancer cells, meaning FTH is an essential YTHDF1 target gene in lung cancer, obviously, in an m6A-dependent manner." (PMID 37259333, 2023). "For example, the overexpression of m6A methyltransferase METTL3 could regulate the expression of the JUNB gene, which contributed to the epithelial-mesenchymal transition (EMT) in lung cancer." (PMID 37047493, 2023). "Accumulating evidence has shown that METTL3 plays a crucial role in the tumorigenesis of lung cancer, dependent or independent of m6A modification." (PMID 35331234, 2022). "METTL3 increases the expression of EGFR and TAZ and promotes the growth, survival, and invasion ability of human lung cancer cells; it also plays a role in promoting the translation of lung cancer oncogenes." (PMID 38089085, 2022). "In addition, METTL3-YTHDF3 complex can improve the stability of MALAT1, and promote the invasion, metastasis and chemoresistance of lung cancer cells through YAP mediated miR-1914-3p." (PMID 35022030, 2022). "YAP could promote the generation of lung cancer stem cells in a METTL3-m6A-YTHDF3-dependent manner, METTL3 could reverse gefitinib resistance of NSCLC by β-elemene." (PMID 36008805, 2022). "According to the study focusing on the role of METTL3 in lung adenocarcinoma, METTL3 could enhance mRNA translation including EGFR and Hippo pathways, further promoting growth and invasion of human lung cancer cells." (PMID 35860263, 2022). "In lung cancer, METTL3 but not METTL14 is significantly elevated in tumors compared to normal tissue." (PMID 36008936, 2022). "METTL3/YTHDF2 reduces the expression of ZBTB4 mRNA in a m6A-dependent manner, enhances the expression of EZH2, induces the EMT, and promotes the proliferation and metastasis of lung cancer." (PMID 35945641, 2022).
lung cancer (continued). "Synergized suppression of intra-pulmonary tumor formation was observed upon knocking out Mettl3 and overexpressing ALKBH5 simultaneously, indicating that Mettl3 and ALKBH5 are critical for maintaining transformative phenotypes in murine lung cancer cells." (PMID 35078505, 2022). "To investigate the mechanism of METTL3 in decreasing sensitivity to gefitinib in PC9 cells and H3255 cells, we checked published methylated RNA immunoprecipitation sequencing and data analysis in lung cancer." (PMID 33491264, 2021). "METTL3 can promote the splicing of the miR-143-3p precursor, which in turn activates the miR-143-3p/VASH1 axis and ultimately leads to the progression and metastasis of lung cancer." (PMID 33643384, 2021). "However, up to now, in lung cancers, only FTO and METTL3 have been reported as potential targets for its diagnosis and treatment 31,32." (PMID 32398949, 2020). "However, another report noted that increases in METTL3 m6A levels enhance the translation of target mRNAs (RGFR and TAZ), promoting the formation of lung cancer." (PMID 31290116, 2019). "It is identified by Lin and colleagues that METTL3 boosts translation of certain mRNAs including epidermal growth factor receptor (EGFR) and the Hippo pathway effector TAZ, thus promoting growth, survival, and invasion of human lung cancer cells." (PMID 29587823, 2018). "STM2457, a compound that reduces m6A modification by suppressing the METTL3/METTL14 complex, has shown good antitumor effects in malignant tumors including leukemia, cholangiocarcinoma, and osteosarcoma and has shown potential in reversing liver and lung cancer resistance." (PMID 39268503, 2024). "We further identified RAC3 as a downstream target of METTL3, and RAC3 facilitates NSCLC cell migration via the AKT/NF-κB pathway, suggesting that RAC3 m6A modification may serve as a potential therapeutic target for lung cancer treatment." (PMID 37056933, 2023). "The study found that METTL3 and METTL14 interact with chromatin and the transcriptional machinery, suggesting that disruption of this process could lead to the development of diseases, such as lung fibrosis and lung cancer metastasis." (PMID 38133427, 2023). "Notably, the expression of a METTL3 derivative without the eIF3h interacting region is not able to induce tumors in lung cancer cell line xenograft models; thus, indicating the important role of cytoplasmic regulation of translation by METTL3 in tumorigenesis." (PMID 36012237, 2022). "Interestingly, METTL3, as the only catalytically active subunit of the methyltransferase complex, promotes the development of lung cancer dependent or independent of catalytic activity." (PMID 35331234, 2022). "METTL3, as an RNA methyltransferase, promotes the translation of certain mRNAs, incorporating the Hippo pathway effector TAZ and epidermal growth factor receptor (EGFR) among human cancer cells, which promotes growth, invasion, and survival in human lung cancer cells." (PMID 34150845, 2021). "Interestingly, in addition to m6A methyltransferase activity, METTL3 also promotes the translation of target transcripts in lung cancer cells independent of its catalytic activity." (PMID 32429972, 2020). "Lin and colleagues identified that both wild-type and catalytically inactive METTL3 can boost the translation of some particular mRNAs such as epidermal growth factor receptor (EGFR) and the Hippo pathway effector TAZ, thus promoting the development of lung cancer." (PMID 32760220, 2020). "A previous study demonstrated that METTL3 directly associates with the translation machinery and enhances the translation of its target mRNAs (RGFR and TAZ) independent of its methyltransferase activity in lung cancers." (PMID 33062408, 2020).
lung cancer (continued). "METTL3 itself participates in controlling the translation of some m6A-containing mRNAs, such as the epidermal growth factor receptor, and the expression of the Hippo pathway effector TAZ, thus affecting Myc and RAS levels in lung cancer independently of m6A reader proteins." (PMID 31921660, 2019). "Additionally, METTL3 has also been shown to promote translation in human lung cancer cells independent of its m6A methylation activity." (PMID 30131850, 2018). "Besides being an m6A “writer”, METTL3 may serve as an m6A “reader” in the cytoplasm by identifying and interacting with translation initiation factor, enhancing the translation of EGFR and TAZ in lung cancer." (PMID 33029866, 2020). "Importantly, when we compared the METTL3 level in paired tumor and non-tumor tissues, we found that METTL3 levels in the tumor tissues were significantly higher than those in the non-tumor tissues, suggesting that METTL3 might facilitate lung cancer progression." (PMID 37056933, 2023).